RGS5 (regulator of G protein signaling 5)
Description:
Inhibits signal transduction by increasing the GTPase activity of G protein alpha subunits thereby driving them into their inactive GDP-bound form. Binds to G(i)-alpha and G(o)-alpha, but not to G(s)-alpha (By similarity).
Synonyms: MST092; MST106; MST129; MSTP032; MSTP092; MSTP106; MSTP129
Tractability: Antibody: its Gene Ontology location is reachable by antibodies, with high confidence.
Gene: Protein-coding gene on chromosome 1 (163,111,121 to 163,321,791, reverse strand). Ensembl gene ENSG00000143248.
Subcellular location: Cytoplasm (Isoform 1); Membrane; Cytoplasm (Isoform 2)
Subcellular location (Human Protein Atlas): Cytosol; Vesicles
Pathways (Reactome):
Signal Transduction: G alpha (i) signalling events; G alpha (q) signalling events
Gene Ontology:
Molecular function: protein binding; GTPase activator activity; GTPase activity
Biological process: G protein-coupled receptor signaling pathway; negative regulation of G protein-coupled receptor signaling pathway; regulation of G protein-coupled receptor signaling pathway; negative regulation of vascular associated smooth muscle cell proliferation
Cellular component: cytoplasm; cytosol; membrane; cytoplasmic side of plasma membrane; plasma membrane
Genetic constraint (gnomAD): Loss-of-function variants: 11 observed, 11.21 expected, observed/expected ratio (o/e) 0.98, 90% interval 0.62 to 1.6. The upper end of that interval is the gene's LOEUF score, 1.6, which puts it in group 6 of 6, group 1 being the genes least tolerant of losing a copy. Missense variants: 168 observed, 185.64 expected, observed/expected ratio (o/e) 0.9, 90% interval 0.8 to 1.03. Synonymous variants: 47 observed, 64.07 expected, observed/expected ratio (o/e) 0.73, 90% interval 0.58 to 0.94.
Homologues: Orthologues: chimpanzee RGS5 (94% identical), rabbit RGS5 (94% identical), guinea pig RGS5 (93% identical), macaque RGS5 (92% identical), mouse Rgs5 (90% identical), rat Rgs5 (90% identical), tropical clawed frog rgs5 (80% identical), pig RGS5 (78% identical), zebrafish rgs5a (71% identical), dog RGS5 (64% identical). Paralogues in human: RGS3 (53% identical), RGS16 (51% identical), RGS4 (51% identical), RGS8 (46% identical), RGS18 (45% identical), RGS2 (45% identical), RGS1 (41% identical), RGS21 (40% identical), RGS7 (36% identical), RGS9 (36% identical), RGS20 (35% identical), RGS11 (35% identical), and 11 more.
Diseases named in the same sentence as RGS5 in open-access papers:
RGS5 is named in the same sentence as 104 diseases in open-access papers, as found by Europe PMC text mining. Sharing a sentence is not in itself a finding about the gene and the disease. The quoted sentences say what the papers report.
Stroke (13 papers, 2007 to 2025). Sudden impairment of blood flow to a part of the brain due to occlusion or rupture of an artery to the brain. "We have previously shown reduced BBB leakage in RGS5-KO mice in the acute phase after stroke, indicating that loss of RGS5 has an impact on both early and late BBB dysfunction after stroke." (PMID 31039042, 2019). "Using RGS5–knockout (KO) mice, we study how loss of RGS5 affects the pericyte response and vascular remodeling in a stroke model at 7 d after ischemia." (PMID 31039042, 2019). "In line with this, we have previously shown that loss of RGS5 in the acute phase of stroke results in increased numbers of perivascular pericytes and preserved tight junctions." (PMID 31039042, 2019). "Our data add to these findings and demonstrate that loss of RGS5 improves vascular integrity and, associated with this, results in reduced vascular leakage in the chronic phase after stroke." (PMID 31039042, 2019). "First, we asked whether loss of RGS5 leads to changes in the morphology of PDGFR-β+ cells at 7 d after stroke." (PMID 31039042, 2019). "The loss of regulator of G protein signaling 5 (RGS5) has been associated with increased pericyte number and improved BBB function in a mouse model of stroke, suggesting a role for RGS5 in brain pericyte loss during stroke." (PMID 37566011, 2023). "As such, RGS5 is needed for normal embryonic vessel and BBB formation, whereas in adult stroke pathology, RGS5 expression and hypoxic RGS5 protein stabilization leads to adverse stroke outcome." (PMID 36982744, 2023). "In a permanent MCAO stroke model using RGS5-GFP mice GFP+ cells were immuno-positive for microglial markers." (PMID 32843103, 2020). "Our data demonstrate that RGS5 in brain pericytes plays an important role in modulating the pericyte response to stroke." (PMID 31039042, 2019). "This is supported by our previous finding that loss of RGS5 results in increased numbers of PDGFR-β+ pericytes in the acute phase of stroke and that pericytes express RGS5 before detaching from the blood vessel wall in stroke." (PMID 31039042, 2019). "To assess changes in PDGFR-β signaling activation, we performed Western blot analysis to examine the expression of total PDGFR-β protein and pPDGFR-β (Tyr751) in the infarct area of WT and RGS5-KO mice at 7 d after stroke." (PMID 31039042, 2019). "Consistent with our results in rodents, we found that pericytes expressed RGS5 in human stroke samples and showed an activated morphology with a round cell body." (PMID 24848101, 2014). "Rgs5 has also been identified in endothelial cells of cerebral capillaries where it was downregulated in stroke-prone SHR compared to SHR." (PMID 17986358, 2007). "Extending previous studies by our group investigating functions of pericytes in ischemic stroke, we here perform a further characterization and an in-depth analysis of the molecular response of RGS5-expressing pericytes to ischemic stroke using the same stroke model, pMCAO." (PMID 37378751, 2024). "Interestingly, knockout of RGS5 in pericytes prevents their migration from the capillaries after stroke, resulting in significantly reduced BBB leakage after stroke or vessel stabilization in tumors." (PMID 36982744, 2023). "However, microglia were reported to transiently express non-microglial genes upon activation, therefore, it was possible that the RGS-5 promoter was somehow induced in microglia after stroke, enabling the GFP expression." (PMID 32843103, 2020). "RGS5 may constitute a target to normalize the pericyte response, preserve the vasculature, and reduce vascular leakage in the chronic phase after stroke." (PMID 31039042, 2019). "Next, we investigated whether the vascular preservation in RGS5-KO mice was accompanied by changes in vascular leakage after stroke." (PMID 31039042, 2019).
Stroke (continued). "Loss of RGS5 leads to a shift toward an increase in the number of perivascular pericytes and reduction in the density of parenchymal PDGFR-β–expressing cells associated with normalized PDGFR-β activation after stroke." (PMID 31039042, 2019). "We demonstrate that RGS5–knockout (KO) mice have higher pericyte coverage of blood vessels, preservation of vessel length, and a significant reduction in vascular leakage at 7 d after stroke compared with wild-type (WT) mice." (PMID 31039042, 2019). "In addition, we show in human stroke that pericytes express RGS5 and co-express the macrophage/microglial marker galectin-3 (GAL-3)." (PMID 24848101, 2014). "RGS5 is involved in neurological disorders, including diseases of Huntington’s (HTT), Parkinson’s disease (PD), Alzheimer’s disease (AD), stroke, and so on." (PMID 39469623, 2024). "Here we demonstrate that lack of RGS5 in brain pericytes has a clear impact on PDGFR-β+ pericyte response after stroke." (PMID 31039042, 2019). "RGS5 has been suggested to regulate PDGFR-β signaling in vitro; however, its potential role in the regulation of PDGFR-β signaling in pericytes and its impact on vascular remodeling in the chronic phase after stroke remains elusive." (PMID 31039042, 2019). "Here we investigate the effect of RGS5 on pericytes in the chronic phase after stroke and demonstrate that lack of RGS5 in pericytes clearly modifies the pericyte response at 7 d after stroke." (PMID 31039042, 2019). "Using WT and RGS5-KO mice, we provide clear evidence that absence of the protein RGS5 in brain pericytes changes the spatial distribution of pericytes in stroke." (PMID 31039042, 2019). "Regulator of G-protein signaling 5 (RGS5) has been associated with pericyte detachment from the vascular wall, but whether it regulates pericyte function and vascular stabilization in the chronic phase of stroke is not known." (PMID 31039042, 2019).
Hypertension (10 papers, 2007 to 2025). The presence of chronic increased pressure in the systemic arterial system. "These cells express a regulator of G-protein signaling, RGS5, loss of which results in hypertension and hyperresponsiveness to vasoconstrictors and vascular stiffening, which indicates a causal role for RGS5 in vascular homeostasis." (PMID 38899223, 2024). "RGS5 is also involved in ion transport mechanisms in the kidney and has been associated with the regulation of blood pressure or hypertension." (PMID 32431860, 2020). "RGS5-deficient mice exhibit enhanced arterial hypertrophy and perivascular fibrosis in a hypertension-induced vascular injury model." (PMID 25290689, 2014). "Hence, RGS5 is an important contributor to high blood pressure, and hypertension is one of the most common risk factors of renal disease." (PMID 32431860, 2020). "Xiao et a.l reported that multiple SNPs in combination in RGS5 may confer risk for hypertension in Chinese population." (PMID 21698121, 2011). "In mice, homozygous knockout of Rgs5 elicited hypertension that was exacerbated during pregnancy, whereas mice with heterozygous disruption were not challenged with hypertension until pregnant." (PMID 41416997, 2025). "Previous studies have demonstrated that RGS5 is involved in vascular remodeling in tumors, hypertension and atherosclerosis via regulation of cellular stress responses, proliferation and constriction, inflammatory response, and vascular barrier function." (PMID 35320283, 2022). "Arterial hypertension appears to downregulate Rgs5 expression in angiotensin II-treated mice while the opposite was observed in deoxycorticosterone acetate (DOCA)-treated hypertensive mice indicating a context-dependent regulation." (PMID 34359918, 2021). "Recently, the blockage of RGS5 has been suggested to provide an alternative approach to treat hypertension but the biological impact of the reduced expression of RGS5 in the plaques is not known." (PMID 22509262, 2012). "However, phenotype changes of VSMCs evoked by biomechanical stretch or wall stress as it occurs during hypertension-induced structural remodeling of the arterial wall were impaired in mice upon knockdown of Rgs5." (PMID 34359918, 2021). "Moreover, proliferation of VSMCs is controlled by RGS5 during neointima formation and our own studies revealed the ability of RGS5 to stimulate RhoA activity in VSMCs in the context of arterial hypertension." (PMID 34359918, 2021). "In summary, upregulation of RGS5 may be a promising treatment for preventing HCMV-induced hypertension." (PMID 32041970, 2020). "A study demonstrated that RGS5 may be a candidate target gene for the treatment of human and animal hypertension." (PMID 32041970, 2020). "The data indicated that several DEGs, including prostaglandin I2 (prostacyclin) synthase (PTGIS), RGS5, selectin E (SELE), endothelin converting enzyme (ECE), and ATPase, Na+/K+ transporting, and beta 1 polypeptide (ATP1B1), were highly associated with hypertensive disease." (PMID 32041970, 2020). "However, changes in common to caveolin-1 expression and G protein signalling, through attenuation of Rgs2 and Rgs5, may contribute to hypertension through augmentation of vasoconstrictor pathways and provide potential targets for common drug development." (PMID 17986358, 2007).
cardiac hypertrophy (8 papers, 2012 to 2024). "Cardiac-specific overexpression of RGS5 in transgenic mice effectively alleviates the damage caused by cardiac hypertrophy and fibrosis." (PMID 33892733, 2021). "Similarly, loss of RGS5 has been reported to be associated with tachyarrhythmia and cardiac hypertrophy in mice." (PMID 35745791, 2022). "Transgenic mice with cardiac-specific overexpression of human Rgs5 gene were resistant to cardiac hypertrophy and fibrosis via inhibition of MEK-ERK1/2 signaling." (PMID 33892733, 2021). "RGS5 prevents cardiac hypertrophy through inhibition of MEK-ERK1/2 signaling, especially in hyperglycemic environments." (PMID 34233591, 2021). "RGS5 can switch off G-protein mediated signaling pathway, thereby preventing cardiac hypertrophy, atherosclerosis, and angiogenesis." (PMID 25610490, 2014). "Previous studies also indicated the activity of RGS5 to regulate cardiac hypertrophy, atherosclerosis, and vascular remodeling." (PMID 25610490, 2014). "Our previous work showed that Rgs5−/− mice promoted cardiac hypertrophy and fibrosis due to the activation of the MEK-ERK1/2 signaling pathway." (PMID 23144791, 2012). "The effect of regulator of G protein signaling 5 (RGS5) on cardiac hypertrophy, atherosclerosis and angiogenesis has been well demonstrated, but the role in the development of obesity and insulin resistance remains completely unknown." (PMID 22272317, 2012). "Functional diversity may exist among RGS proteins and RGS5 is an important member of the RGS protein superfamily that has recently been reported to regulate cardiac hypertrophy, atherosclerosis and angiogenesis through the inhibition of several Gαi- and Gαq-mediated signaling pathways." (PMID 22272317, 2012). "Our previous study demonstrated that Rgs5 transgenic mice were resistant to cardiac hypertrophy and fibrosis through inhibition of MEK-ERK1/2 signaling, whereas Rgs5−/− mice displayed the opposite phenotype in response to pressure overload." (PMID 23144791, 2012).
lung cancer (8 papers, 2011 to 2025). A malignant neoplasm involving the lung. "For instance, an association between high expression levels of RGS5 and poor outcomes have been observed in a study of human lung cancer, while studies on non-small cell lung cancer and epithelia ovarian cancer reported a link between a high expression levels of RGS5 and better survival months." (PMID 32431860, 2020). "RGS5 encodes for a negative regulator of G-protein signaling implicated in vascular normalization, invasion and metastasis and its involvement was shown in breast and lung cancer." (PMID 23308108, 2013). "For example, overexpression of RGS1 inhibited CXCL12-mediated human plasmacytoma cell migration, and epigenetic inhibition of RGS2 has been associated with prostate cancer progression and overexpression of RGS5 on lung cancer cells." (PMID 35646090, 2022). "One possibility is that the UBA6–UBE2Z cascade also induced the turnover of tumor-suppressor proteins RGS4 and RGS5, which are both shown to be related in lung cancer." (PMID 34199813, 2021). "As a GTPase-activating protein of the heterotrimeric Gq and Gi proteins, RGS4 and RGS5 are all tumor-suppressor proteins and have been shown to be low expressed in non–small-cell lung cancer (NSCLC)." (PMID 34199813, 2021). "In contrast to these two study, it has been found that over-expression of RGS5 gene in the human lung cancer cells decreases the survival rate, and increases the cytotoxic result of radiation." (PMID 32431860, 2020). "M5 expressed pericyte-associated genes (RGS5, PDGFRB, NES, THY1, KCNJ8) and showed strong similarity to curated pericyte signatures, including pan-cancer C8_RGS5 pericytes, healthy human prostate pericytes and pericytes from lung cancer." (PMID 41378308, 2025). "Significantly, abnormal expression of multiple RGS proteins, such as RGS17 in hepatocellular carcinoma, lung cancer, and prostate cancer, RGS5 in ovarian cancer and squamous cell carcinoma, and RGS6 in breast cancer and urinary bladder cancer, has been documented in relation to tumor progression." (PMID 38906869, 2024). "Therefore, it is biologically plausible that RGS4, RGS5, and RGS12 are associated with lung cancer survival." (PMID 21698121, 2011).
ovarian carcinoma (8 papers, 2010 to 2024). A malignant neoplasm originating from the surface ovarian epithelium. "RGS5 (regulator of G protein signaling 5), a family of GTPase activating proteins, is extensively up-regulated in a variety of malignant cells, including non-small cell lung cancer, renal cell carcinoma, and ovarian cancer, and is associated with tumor growth and poor prognosis." (PMID 36561319, 2022). "We thus constructed an inducible gene expression system to achieve RGS5 expression in HeyA8-MDR ovarian cancer cells." (PMID 22792465, 2012). "Taken together, these data suggest that RGS5 expression reduces the proliferative capacity of HeyA8-MDR ovarian cancer cells." (PMID 22792465, 2012). "This suggests that RGS5 functions as a key mediator in the carcinogenesis of ovarian cancer." (PMID 37649067, 2023). "RGS5 was reported to reduce ovarian cancer cell proliferation and NSCLC cell metastasis." (PMID 29108247, 2017). "We thus questioned whether the inducible expression of RGS5 in a tumor model of ovarian cancer might counter the effects observed in knockout mice and support a longer period of survival in vivo." (PMID 22792465, 2012). "Future studies might explore the roles of combinations of RGS5 with other RGS proteins in ovarian cancer." (PMID 22792465, 2012). "Taken together, these data show that RGS2, RGS10, and RGS17 transcripts are commonly downregulated in acquired chemoresistance in three distinct ovarian cancer cell lines resistant to three distinct chemotherapeutics, while RGS5 was down-regulated in two of the models." (PMID 21044322, 2010). "RGS5 reduces proliferation of cancer cell derived primary endothelial cells via MAPK/ERK signaling pathway under hypoxia in ovarian cancer." (PMID 36561319, 2022). "In addition to RGS2, other RGS proteins such as RGS5, RGS10 and RGS17 are also closely related to ovarian cancer." (PMID 37649067, 2023). "Through this we observed that inducible RGS5 expression significantly reduces in vitro BrdU-positive HeyA8-MDR cells, although this did not correlate with a reduction in tumor volume observed using an in vivo mouse model of ovarian cancer." (PMID 22792465, 2012).
atherosclerosis (7 papers, 2012 to 2025). A disease characterized by the build-up of fatty material and calcium deposition in the arterial wall resulting in partial or complete occlusion of the arterial lumen. "Previous studies have shown that miR-320a aggravates atherosclerosis by inhibiting RGS5 and promoting cell viability, migration, and proliferation of ox-LDL-induced VSMCs." (PMID 38886631, 2024). "RGS5 has been reported to regulate atherosclerosis, angiogenesis, and inflammation through G-protein coupled receptor (Gαi and Gαq) mediated signal transductions." (PMID 25610490, 2014). "Our finding revealed the antiatherosclerosis of Korean red ginseng extract may involve RGS5 signaling which could also be the possible intracellular target against chronic inflammation prone to atherosclerosis." (PMID 25610490, 2014).